ENSG00000280554
Gene: Small nucleolar RNA gene on chromosome 15 (66,502,019 to 66,502,089, reverse strand). Ensembl gene ENSG00000280554.
Gene Ontology:
Biological process: RNA processing
Cellular component: nucleolus
Homologues: Orthologues: mouse Gm22571 (89% identical).